SMAD4 (SMAD family member 4)
Diseases named in the same sentence as SMAD4 in open-access papers (continued):
Sharing a sentence is not in itself a finding about the gene and the disease.
colorectal cancer (continued). "Critical components of transforming growth factor β pathway signaling, along with related proteins SMAD2 and SMAD3; SMAD4 and SMAD2 are located on chromosome 18q, a frequent site of loss of heterozygosity in colorectal cancers; inactivated by homozygous deletion or mutation." (PMID 25713610, 2014). "Subgroup analyses revealed that unfavorable CSS/RFS with loss of Smad4 staining was also found in colorectal cancer, regardless of the number of participants." (PMID 25333693, 2014). "In view of case reports and evidence that colorectal cancer risks are higher for patients with SMAD4 mutations, we were surprised that the risk of colorectal cancer did not emerge more strongly for participants and/or relatives with HHT." (PMID 24354965, 2013). "Although homozygous deletions or intragenic mutations account for up to 60% of the SMAD4 inactivation in pancreatic and colorectal carcinoma, no homozygous deletion and only 6% of intragenic mutations of SMAD4 were detected in HCC." (PMID 23922662, 2013). "Inactivating mutations in SMAD2 and SMAD4 are frequent especially in pancreatic and colorectal carcinomas, although they do not stand for the most frequent tumor changes." (PMID 22943793, 2012). "Based on current understanding, mutations in SMAD3 are absent in almost all cancer types while mutations of SMAD4 are frequent in pancreatic and colorectal cancers but rare in breast cancer." (PMID 21835029, 2011). "Smad4 is a tumour suppressor frequently inactivated in pancreatic and colorectal cancers." (PMID 17997817, 2007). "In addition, prior studies have demonstrated the presence of SMAD4 genetic alterations among colorectal carcinoma and cholangiocarcinoma in only 11–17% and 45.2% of cases, respectively." (PMID 17587453, 2007). "Although functional inactivation of Smad4 in colorectal cancer frequently occurs at late stages when tumours acquire invasive and metastatic capabilities, the roles of TGF-β signals in carcinogenesis are complex and also comprise tumour-promoting functions in colorectal carcinogenesis." (PMID 15785755, 2005). "Our findings of less than 5% point mutations are at the lower end of the spectrum and confirm the low frequency of point mutations of Smad4 in early-stage colorectal cancer without distant metastasis." (PMID 12569386, 2003). "Other possible explanations for the absence of Smad4 point mutations in colorectal cancer at this stage include methylation changes at the promoter and alternative splicing or changes in mRNA stability." (PMID 12569386, 2003). "Biologically, the results reinforce the dual role of TGF-β signaling in colorectal cancer: functioning as a tumor suppressor in early stages, but shifting toward pro-metastatic, immune-evasive, and chemoresistant roles when disrupted through alterations in key regulators such as SMAD4 and BMPR1A." (PMID 41009631, 2025). "We tested whether the co-existing mutational context with and without SMAD4 variants in colorectal cancer altered SMAD4 dependent gene expression and key regulatory gene expression pathways." (PMID 40348815, 2025). "This study investigated the transcriptional regulation of the SMAD4 gene in colorectal cancer in search of the differentially regulated transcripts that could serve as biomarkers, their potential roles in malignant cells and the mechanism responsible for their differential expression." (PMID 39132157, 2024). "SMAD4 gene transcriptional regulation, including alternative transcription initiation, splicing, polyadenylation and translation initiation, remains another yet unexplored mechanism that could be involved in the onset and progression of colorectal cancer." (PMID 39132157, 2024).
colorectal cancer (continued). "Thus, we aimed to explore this phenomenon at the cellular level on the example of a major tumor suppressor SMAD4 in search of molecular mechanisms in colorectal cancer that could be exploited for novel biomarkers or therapeutic approaches." (PMID 39132157, 2024). "A recent study has demonstrated that SMAD4 mutations do not prevent colorectal cancer EMT." (PMID 38904097, 2024). "Although SMAD4 is a transcription factor critical to canonical TGF-β and Bone morphogenetic protein (BMP) signaling activity, overexpression of the EMT-TF SNAI1 in SMAD4-mutant colorectal cancer cells compensated for this deficiency, inducing cancer cell elongation and invasion in vitro." (PMID 38067168, 2023). "SMAD4 is located at 18q21 and may be a tumor suppressor in colorectal cancer." (PMID 35565354, 2022). "They found that the majority of colorectal cancers expressed SMAD4 and TGF-β1 and suggested that hypoxia-induced TGF-β1 production by tumor cells may suppress the tumor-infiltrating immune cells and contribute to their invasiveness through autocrine activation of Smad signaling." (PMID 34012911, 2021). "LOH at 18q indicates presence of several TSGs including Deleted in Colorectal Carcinoma (DCC), SMAD2, and SMAD4; loss of expression of 18q LOH plays a significant role in CRC pathogenesis." (PMID 33374459, 2020). "Mechanistically, TRIM47 promotes the ubiquitination and degration of SMAD4 by interacting with SMAD4, and further increases the levels of C-C motif chemokine ligand 15 (CCL15) and C-C motif chemokine receptor 1 (CCR1), ultimately causing poor outcome of colorectal cancer." (PMID 30979374, 2019). "Similarly, Smad2 and Smad4 proteins had ability to inhibit the growth of colorectal cancer." (PMID 30792708, 2019). "It has been established that ubiquitination and subsequent proteasomal degradation of SMAD4 facilitate tumor progression by endorsing EMT and cell migration in PAAD and colorectal cancer." (PMID 39143229, 2025). "The interaction and methylation of SMAD4 by the oncogene protein arginine methyltransferase 5 (PRMT5) are essential for driving TGF-β1-induced EMT and promoting metastasis in colorectal cancer (CRC)." (PMID 40109873, 2025). "In colorectal cancer (CRC), PSG9 has been shown to promote angiogenesis through interaction with SMAD4, leading to enhanced nuclear retention of SMAD4 and activation of angiogenesis-related genes such as VEGFA and PDGF-AA." (PMID 40806565, 2025). "In colorectal cancer, the interplay between cAMP-PKA/EPAC signalling and the TGFβ/SMAD4 pathway regulates stemness and metastatic potential, highlighting its critical role in cancer progression." (PMID 40699738, 2025). "In colorectal cancer, PRMT5 facilitates the metastasis of tumor cells through the methylation of SMAD4." (PMID 41463372, 2025). "AGR2 expression was inversely related to SMAD4 status in PDAC and colorectal cancer cell models and was secreted from cells into their media." (PMID 39727484, 2024). "A 2015 study reported that 5-FU chemoresistance was promoted through low Smad4 expression which activate PI3K/Akt/CDC2/survivin cascade and reduce cell cycle arrest in colorectal cancer cells." (PMID 39706834, 2024).
colorectal cancer (continued). "SMAD4 is a key transcriptional factor of TGF‐beta pathway and acts as a tumor suppressor gene in colorectal cancer." (PMID 36653904, 2023). "Patients and methods: The effect of 5-FU on the expression of SMAD4 and TGFB1 in colorectal cancer cells derived from the CACO-2, SW480 and SW620 cell lines was evaluated using real-time PCR." (PMID 37237640, 2023). "LINC00941 forms a complex with SMAD4 and prevents degradation of SMAD4 protein, resulting in activation of TGF-β/SMAD2/3 signaling pathway and consequently promotes metastasis of colorectal cancer." (PMID 36717549, 2023). "In colorectal cancer, miR-34a directly targets the 3′-UTR of SMAD4 and represses signaling via TGF-β/SMAD4." (PMID 34917620, 2021). "Although the mechanisms that enable NK cells to restrain colorectal cancer (CRC) are unclear, the current study suggests the involvement of Smad4." (PMID 33424832, 2020). "For example, two tumor suppressors frequently inactivated in colorectal cancer, SMAD2 and SMAD4, belong to the same protein family and are located within several megabases of each other." (PMID 30697341, 2019). "CXCR4, SMAD4, and KRAS coexpressed with hsa-miR-224-5p were enriched in pathway of Intestinal immune network for IgA production and colorectal cancer." (PMID 31073530, 2019). "Mutations of SMAD2 are infrequent in cancer, they are found in a small fraction of colorectal carcinoma, while, on the other hand, SMAD4/DPC4 is considered an important tumor-suppressor gene." (PMID 31238579, 2019). "Here, we demonstrated that TGF-β1 elevated the expression of miR-155 in colorectal cancer cells through SMAD3 and SMAD4." (PMID 27626488, 2016). "TGFBR2 and SMAD4 are involved in the transforming growth factor (TGF)-β pathway and were identified as driver genes in gastric cancer and colorectal cancer." (PMID 26374103, 2015). "The protein expression patterns of TGF-β and SMAD4 in different cell groups were similar to the patterns observed for the respective mRNA, suggesting that PZH inhibits colorectal cancer cell MDR/EMT probably through suppression of TGF-β signaling pathway." (PMID 25505925, 2014). "Smad4 is a critical participator in the regulation of TGF-β1 signaling and it has been reported to be a target of miR-454 in colorectal cancer cells." (PMID 24685242, 2014). "Chromosome 18q21.1 harbours the tumour suppressor genes SMAD4, SMAD2 and deleted in colorectal cancer (DCC) genes." (PMID 23110075, 2012). "However, whether Smad4 plays a key role in tumorigenesis of colorectal cancer is still unclear." (PMID 12569386, 2003). "Moreover, miR-20a promotes epithelial–mesenchymal transition by suppressing the expression of genes such as SMAD4 and GABBR1, thereby facilitating invasion in colorectal cancer." (PMID 40693022, 2025). "SMAD4, ID1, SPP1 and PAK3 mRNA expression also appeared to have prognostic implications for colorectal cancer using the TCGA cohorts, and with further evaluation required in extended human cohorts, are candidate functional readouts associated with disruption of the TGF-β-BMP-SMAD4 pathway." (PMID 40348815, 2025).
colorectal cancer (continued). "Furthermore, SMAD4 overexpression enhances NKG2D activation via YTHDF2 upregulation, thereby potentiating NK cell cytotoxicity against colorectal cancer cells through the SMAD4/YTHDF2 regulatory axis." (PMID 40986143, 2025). "Experimental approaches such as CRISPR-based knockout or knock-in of SMAD4 and BMPR1A in colorectal cancer cell lines and patient-derived organoids could directly test their effects on chemoresistance and tumor progression." (PMID 41009631, 2025). "While usually SMAD4 loss alone does not initiate tumor formation, it promotes progression after cancer is initiated by other oncogenes like KRAS in PDAC and APC in colorectal cancer." (PMID 38666907, 2024). "In CRC (Colorectal Cancer), APC and SMAD4 are also identified as the candidates." (PMID 38062391, 2023). "Previous studies have shown that BMP signaling in the absence of SMAD4 leads to the activation of a broad range of non-canonical signaling pathways and to enhancement of invasion and metastasis in colorectal cancer." (PMID 35902550, 2022). "Several studies have correlated the absence of SMAD4 to worse prognosis in patients with early-stage colorectal cancer." (PMID 35892903, 2022). "BGN expression is increased in many cancers including bladder cancer, colorectal cancer, gastric cancer, esophageal cancer, prostate cancer, and endometrial cancer and various factors modulate its expression, including p38, HIF-1, TGF-β/Smad4, and NF-κB." (PMID 32050430, 2020). "Further PPI analysis indicated that SMARCD3 might promote colorectal cancer metastasis through MAPK14, MYOD1 or SMAD4 related pathways." (PMID 33125346, 2020). "Along with SMAD4, APC is another important gene in colorectal cancer." (PMID 30709382, 2019). "Our result showed that the expression of Smad2 (not Smad4) protein was up-regulated after T. gondii infection, which indicated the enhanced ability against colorectal cancer." (PMID 30792708, 2019). "As a potent tumour suppressor in colorectal cancer (CRC), SMAD4 is regulated by many miRNAs." (PMID 28655924, 2017). "The impact of SMAD4 deficiency on the development of CIN phenotype is not clear; SMAD4 mutations in colorectal cancer probably occur before chromosomal instability, but after divergence of the microsatellite instability pathway." (PMID 27276710, 2016). "However, MDR-induced upregulation of TGF-β and SMAD4 expression was significantly suppressed by PZH treatment, suggesting that PZH suppresses TGF-β pathway in drug-resistant colorectal cancer cells." (PMID 25505925, 2014). "Even in combination with changes in SMAD-4, the observed frequency was not sufficient to account for all 18q21 deletions in colorectal cancers." (PMID 9820171, 1998). "Based on the observed dysregulation of SMAD4-209 and SMAD4-213 in malignant vs. non-malignant colon cells, we propose that their expression ratio might be a solid biomarker candidate for colorectal cancer detection." (PMID 39132157, 2024). "SMAD4 has been suggested as a central component of EMT transition in human colorectal cancer, but in absence of SMAD4, alternative factors may take over the gene regulatory functions of SMAD4 to drive EMT." (PMID 37377893, 2023). "A recent study reported that circPTEN1 bound the MH2 domain of SMAD4 to impair the physical interaction of the circRNA with SMAD2/3, which inhibited the formation and nuclear translocation of SMAD complexes and subsequently inhibited the transcription of TGF-β induced EMT genes in colorectal cancer." (PMID 37689715, 2023).
colorectal cancer (continued). "The relative abundance of the transcript SMAD4–201 was analyzed in human malignant and non-malignant (adult and fetal) cell lines and tissue samples in order to explore its translational potential for colorectal cancer diagnostics." (PMID 35034624, 2022). "Similarly, colorectal cancer cells also manifest overexpressed miR-100-5p level that is regulated by lncRNA PGM5 antisense RNA 1, and miR-100-5p upregulation strengthens proliferation, migration, and invasion through lowering SMAD4 level in cells." (PMID 34218800, 2021). "Hence, we inferred that hsa-miR-224-5p-CXCR4/SMAD4/KRAS interactions play a pivotal role in the development of RSCOAD and LSCOAD by regulating pathway of intestinal immune network for IgA production and colorectal cancer." (PMID 31073530, 2019). "For example, APC promoter methylation may be a potential biomarker for the carcinogenesis of colorectal cancer, SMAD4 expression was a prognostic marker for survival in colorectal cancer patients, and the overexpression of CXCR4 reduced overall survival in colorectal cancer patients." (PMID 27504822, 2016). "For instance, SMAD4 loss alone may not initiate tumor formation but can promote tumor progression initiated by other genes, such as KRAS activation in pancreatic ductal adenocarcinoma and APC inactivation in colorectal cancer." (PMID 38666907, 2024). "Subsequently, the overexpression of Smad4 protein mediated by the mRNA nano-lantern could suppress the expression of its downstream oncogenes and play a negative role in the growth and metastasis progression of colorectal cancer." (PMID 36894556, 2023). "Moreover, in colorectal cancer cells, DUSP4 could promote the Smad4 degradation by regulating ubiquitin-related Smad4 degradation, and promote the cell proliferation, migration and invasion by regulating Smad4 degradation via Smad4 gene." (PMID 32897241, 2020). "However, it cannot be completely ruled out that inactivation of Smad4 could be a common genetic event at later stages of colorectal cancer." (PMID 12569386, 2003). "Moreover, deletions of 18q, 8p, 4p and 15q, inactivation of SMAD4, DCC is considered as discussible factor of negative prognosis of colorectal cancer and other tumors." (PMID 27276710, 2016). "However, functional SMAD4 inactivation alone is not sufficient for tumour initiation, but it is thought to promote tumour progression in conjunction with additional alterations, e.g. activating KRAS (pancreatic duct adenocarcinoma) or inactivating APC alterations (colorectal cancer)." (PMID 32198650, 2020).